BTN2A3P (butyrophilin subfamily 2 member A3, pseudogene)
Synonyms: BTN2.3; formerly BTN2A3
Gene: Transcribed unprocessed pseudogene on chromosome 6 (26,422,119 to 26,431,615, forward strand). Ensembl gene ENSG00000124549.
Subcellular location: Membrane
Diseases named in the same sentence as BTN2A3P in open-access papers:
BTN2A3P is named in the same sentence as 2 diseases in open-access papers, as found by Europe PMC text mining. Sharing a sentence is not in itself a finding about the gene and the disease. The quoted sentences say what the papers report.
sarcoidosis (1 paper, 2023). Sarcoidosis is a multisystemic disorder of unknown cause characterized by the formation of immune granulomas in involved organs. "Our eQTL/GWAS analysis also identified rs2393915 in EAs with complicated sarcoidosis associated to BTN3A2, BTN3A3 and BTN2A3P, MHC I-associated genes; other BTNL2 polymorphisms (rs2076530, rs206530), have been previously reported associated to sarcoidosis susceptibility." (PMID 38390497, 2023).
BTN2A3P also shares sentences with these, for which no sentence is quoted: tumor (1 paper).